DOK2 (docking protein 2)
Description:
DOK proteins are enzymatically inert adaptor or scaffolding proteins. They provide a docking platform for the assembly of multimolecular signaling complexes. DOK2 may modulate the cellular proliferation induced by IL-4, as well as IL-2 and IL-3. May be involved in modulating Bcr-Abl signaling. Attenuates EGF-stimulated MAP kinase activation (By similarity).
Synonyms: p56dok-2; Dok-2; p56DOK
Tractability: Small molecule: it has a binding pocket of medium quality. Antibody: its Gene Ontology location is reachable by antibodies, with high confidence; the Human Protein Atlas places it where antibodies can reach. PROTAC: ubiquitination databases record sites on it; its protein half-life has been measured.
Gene: Protein-coding gene on chromosome 8 (21,908,873 to 21,913,960, reverse strand). Ensembl gene ENSG00000147443.
Subcellular location (Human Protein Atlas): Plasma membrane
Pathways (Reactome):
Developmental Biology: RET signaling
Hemostasis: Tie2 Signaling
Gene Ontology:
Molecular function: protein binding; transmembrane receptor protein tyrosine kinase adaptor activity
Biological process: cell surface receptor signaling pathway; Ras protein signal transduction; signal transduction; cell surface receptor protein tyrosine kinase signaling pathway
Cellular component: plasma membrane; cytosol; cytoplasm
Genetic constraint (gnomAD): Loss-of-function variants: 29 observed, 20.82 expected, observed/expected ratio (o/e) 1.39, 90% interval 1.03 to 1.84. The synonymous counts are far from expectation, so gnomAD's model fits this gene poorly and the ratio says little. Missense variants: 682 observed, 532.99 expected, observed/expected ratio (o/e) 1.28, 90% interval 1.2 to 1.36. Synonymous variants: 282 observed, 227.33 expected, observed/expected ratio (o/e) 1.24, 90% interval 1.12 to 1.37.
Homologues: Orthologues: chimpanzee DOK2 (99% identical), macaque DOK2 (95% identical), pig DOK2 (85% identical), dog DOK2 (82% identical), guinea pig DOK2 (75% identical), mouse Dok2 (74% identical), rat Dok2 (73% identical), tropical clawed frog dok2 (42% identical), zebrafish dok2 (41% identical), Drosophila melanogaster Dok (24% identical), Caenorhabditis elegans rog-1 (17% identical), Drosophila melanogaster CG13398 (15% identical). Paralogues in human: DOK1 (35% identical), DOK3 (32% identical), DOK6 (17% identical), DOK4 (17% identical), DOK5 (16% identical), FRS2 (14% identical), FRS3 (13% identical).
Diseases named in the same sentence as DOK2 in open-access papers:
DOK2 is named in the same sentence as 42 diseases in open-access papers, as found by Europe PMC text mining. Sharing a sentence is not in itself a finding about the gene and the disease. The quoted sentences say what the papers report.
lung adenocarcinoma (8 papers, 2013 to 2025). A carcinoma that arises from the lung and is characterized by the presence of malignant glandular epithelial cells. "The overexpression of region-specific DOK2 has been linked to poor prognosis in human astrocytoma and has been recognized as a prognostic gene within the tumor microenvironment of lung adenocarcinomas." (PMID 40668798, 2025). "DOK2 expression is downregulated in human lung adenocarcinoma due to heterozygous genomic loss encompassing the DOK2 gene at the 8p21.3 locus." (PMID 24255704, 2013). "To determine if DOK2 genomic loss was a feature of a specific genomic class of lung adenocarcinoma, we analyzed the relationship of DOK2 loss with mutation of EGFR or KRAS in 199 primary human lung adenocarcinomas." (PMID 24255704, 2013). "DOK2 has tumour suppression roles in several cancer types as it impairs MAPK activation and loss of its expression is associated with poor survival in lung adenocarcinoma, whilst in BCa greater DOK2 expression is associated with significantly longer disease free survival." (PMID 31683867, 2019). "Here we show that genomic loss of DOK2 is associated with EGFR mutations in human lung adenocarcinoma, and we hypothesized that loss of DOK2 might therefore cooperate with EGFR mutations to promote lung tumorigenesis." (PMID 24255704, 2013). "A reduction in the levels of docking protein 2 (DOK2) expression has previously been reported in lung adenocarcinoma and gastric cancer, indicating that this protein acts as a tumor suppressor in solid tumors." (PMID 25435967, 2015). "On the other hand, loss of DOK2 is also observed in EGFR wild-type tumors, and Dok2 null mice do spontaneously develop lung adenocarcinoma." (PMID 24255704, 2013). "Recent sequencing data shows that RASA1 mutations are observed in lung adenocarcinoma (COSMIC database), so further effort should be directed towards understanding the relationship between RASA1, DOK2, EGFR, and KRAS in lung adenocarcinoma." (PMID 24255704, 2013). "DOK2 is a tumour-suppressor gene in lung adenocarcinoma and myelomonocytic leukaemia." (PMID 30206226, 2018). "In addition, mice with combined knockouts of Dok1, Dok2, and Dok3 developed aggressive histiocytic sarcoma or lung adenocarcinoma." (PMID 24523872, 2014). "Recently, we identified DOK2 as a lung adenocarcinoma tumor suppressor gene." (PMID 24255704, 2013). "However, only the association with EGFR mutation was replicated in the TCGA data, suggesting loss of DOK2 is associated with EGFR mutation but not KRAS mutation in human lung adenocarcinoma." (PMID 24255704, 2013). "In addition, there are some genes in other modules that can have very important roles in lung adenocarcinoma, namely DLGAP5, BIRC5, PSMD2, Src, TTK, SENP2, PSMD2, DOK2, FUS among others." (PMID 23874428, 2013). "In contrast, ectopic expression of DOK2 in KRAS-mutant A549 lung adenocarcinoma cells did not suppress tumor growth or activation of RAS." (PMID 24255704, 2013). "We observe human lung adenocarcinomas without copy number loss of DOK2, and expression of mutated EGFR induces tumor formation in Dok2 wild-type mice, albeit more slowly and less effectively than in a Dok2 null genetic context." (PMID 24255704, 2013). "Many other RTKs are known to play a role in lung adenocarcinoma, including ALK and ERBB2, and it is interesting to speculate that DOK2 may also inhibit lung tumorigenesis driven by those oncogenes." (PMID 24255704, 2013).
ovarian carcinoma (7 papers, 2014 to 2025). A malignant neoplasm originating from the surface ovarian epithelium. "A previous study revealed that the loss of DOK2 induces carboplatin resistance in ovarian cancer through the suppression of apoptosis." (PMID 25360158, 2014). "Reduced expression of DOK2 is closely associated with cisplatin resistance in ovarian cancer." (PMID 41231350, 2025). "In addition, DOK2 deficiency in ovarian cancer induced carboplatin resistance by inhibiting the apoptosis of tumor cells, while the expression of DOK2/Ras p21 protein activator 1 was associated with prognosis and quality of life of breast cancer patients." (PMID 36268281, 2022). "Conversely, in ovarian cancer, the upregulation of DOK2 sensitizes ovarian cancer cells to platinum-based drugs, potentially increasing the effectiveness of treatment." (PMID 40668798, 2025). "Epigenetic alterations in the docking protein 2 (DOK2) gene can induce carboplatin resistance in ovarian cancer via suppression of apoptosis." (PMID 38539161, 2024). "For instance, the downregulation of DOK2 expression in lung and colorectal cancer suggests its role as a tumor suppressor, while high DOK2 expression was found in ovarian cancer and melanoma." (PMID 35321466, 2022). "Depletion of DOK2 could inhibit apoptosis induced by chemotherapy and lead to carboplatin resistance in ovarian cancer." (PMID 35321466, 2022).
lung carcinoma (6 papers, 2011 to 2025). "Research has revealed that DOK2 is a target of copy number loss and mRNA downregulation, effectively suppressing the proliferation of lung cancer cells both in vitro and in vivo." (PMID 40668798, 2025). "For instance, loss of docking protein 2 (DOK2) as well as expression of baculoviral IAP repeat-containing 2/3 (BIRC2/3) can facilitate lung cancer cell proliferation and contribute to lung tumor development." (PMID 24650256, 2014). "For instance, loss of docking protein 2 (DOK2) as well as overexpression of baculoviral IAP repeat-containing 2/3 (BIRC2/3) can facilitate lung cancer cell proliferation and contribute to lung tumor development." (PMID 21935476, 2011). "Gene DOK2 is located on chromosome 8p21.3, a genomic region frequently deleted in lung cancer." (PMID 41463415, 2025). "In addition, DOK2, which is a downstream mediator of IL2RG, has been identified as a suppressor of lung cancer cell proliferation." (PMID 23451142, 2013).
colorectal cancer (5 papers, 2015 to 2025). A primary or metastatic malignant neoplasm that affects the colon or rectum. "Based on the abnormal expression of DOK2 in digestive tract tumors such as gastric and colorectal cancers, some researchers established a prognostic evaluation model including DOK2 that effectively identified patients with poor prognosis." (PMID 36268281, 2022). "DOK2 has been identified as a tumor suppressor gene in a number of types of tumors, including gastric adenocarcinoma and acute leukemias, however, little has been reported with regard to DOK2 in colorectal cancer." (PMID 25435967, 2015). "The normal colorectal mucosa and colorectal cancer tissues were evaluated for immunoreactive DOK2 with specific antibodies." (PMID 25435967, 2015). "In conclusion, the present study demonstrated that DOK2 is expressed in the normal gastric mucosa and 66.7% of colorectal cancer samples." (PMID 25435967, 2015). "Accordingly, in the present study, the expression and significance of DOK2 in colorectal cancer was investigated." (PMID 25435967, 2015). "In other contexts, DOK2 may serve as a valuable prognostic marker for patients undergoing curative resection for conditions such as colorectal cancer and gastric adenocarcinoma." (PMID 40668798, 2025). "However, little is known with regard to the significance of DOK2 in patients with colorectal cancer, another type of gastrointestinal cancer." (PMID 25435967, 2015). "The aim of the current study was to determine the significance of DOK2 in colorectal cancer." (PMID 25435967, 2015). "Similarly, DOK2 is the next potential therapeutic target for colorectal cancer treatment, and will undoubtedly yield huge benefits to patients with advanced or recurrent and metastatic colorectal cancer." (PMID 25435967, 2015). "In the colorectal cancer samples, the differentiated-type tumors (including papillary, and well- and moderately-differentiated adenocarcinomas), based on histopathological grade, were significantly more likely to be DOK2(−) than DOK2(+) [DOK2(−), 69.7%; DOK2(+), 30.3%; P=0.001]." (PMID 25435967, 2015).
breast carcinoma (4 papers, 2014 to 2025). "The negative expression of DOK2 was related to poor prognosis and bad clinical parameters of 285 patients with breast cancer, suggesting that DOK2 can be an independent prognostic factor in breast cancer." (PMID 33552156, 2021). "Moreover, DOK2 was found to act as a potential tumor suppressor in human breast cancer." (PMID 25360158, 2014). "Recently, several studies of other DOK proteins such as DOK1, DOK2, and DOK6 participate in the occurrence and development of breast cancer." (PMID 33552156, 2021). "Moreover, the combined negative expression of DOK2 and RASA1 may function as an independent prognostic factor for patients after breast cancer surgery." (PMID 40668798, 2025).
leukemia (3 papers, 2019 to 2022). A malignant (clonal) hematologic disorder, involving hematopoietic stem cells and characterized by the presence of primitive or atypical myeloid or lymphoid cells in the bone marrow and the blood. "As reviewed above, these findings indicate that DOK2 could be associated with infiltrating immune cells in the leukemia microenvironment and render poor prognosis as mediated by specific immune cell infiltration, which is anticipated to be a new immune-related therapeutic target in AML." (PMID 35321466, 2022). "Although DOK2 has been recognized as an indispensable factor in myeloid homeostasis and leukemia pathogenesis, few studies have focused on the correlation of DOK2 with prognostic implications in AML patients." (PMID 35321466, 2022). "RNA-seq data from the CCLE database revealed that the expression level of DOK2 was highest in AML cell lines, followed by other leukemia types, lymphoma, and multiple myeloma." (PMID 35321466, 2022).
colitis (2 papers, 2020 to 2021). Inflammation of the colon. "Furthermore, the loss of DOK2 has been shown to cause severe colitis in an animal model and is altered at the level of DNA methylation in ulcerative colitis and Crohn’s disease in humans." (PMID 33308304, 2020). "Recently, other members of the DOK family of proteins, namely DOK1 and DOK2, have been shown to regulate colitis severity through inhibiting the expression of Th17 cytokines IL17A and IL22 in DOK1/2 double knockout mice." (PMID 34743196, 2021).
gastric cancer (2 papers, 2015 to 2022). A primary or metastatic malignant neoplasm involving the stomach. "A previous study indicated the clinical significance of DOK2 in evaluating the prognosis of gastric cancer patients." (PMID 25435967, 2015). "The expression level of DOK2 was decreased in gastric cancer, indicating that DOK2 may be a potential tumor suppressor in solid tumors." (PMID 36268281, 2022).
histiocytic sarcoma (2 papers, 2012 to 2014). An aggressive malignant neoplasm with a poor response to therapy, usually presenting as stage III/IV disease. "A recent report showed that mice with coincident loss of Dok-1, Dok-2 and Dok-3 genes develop highly invasive and transplantable histiocytic sarcoma endogenously, and Dok-1/2/3−/− macrophages demonstrate enhanced proliferation ability, suggesting origination of the disease in monocytic cells." (PMID 22952867, 2012).
melanoma (2 papers, 2022 to 2024). A malignant, usually aggressive tumor composed of atypical, neoplastic melanocytes. "To evaluate the role of DOK1 and DOK2 depletion in physiology and effector function of CD8+ T lymphocytes and in cancer progression, we established a transgenic T cell receptor mouse model specific to melanoma antigen hgp100 (pmel-1 TCR Tg) in WT and Dok1/Dok2 DKO (double KO) mice." (PMID 38956389, 2024).
Obesity (2 papers, 2010 to 2018). Accumulation of substantial excess body fat. "Among the genes affiliated with the 119 significant CpGs, SOCS3 and DOK2 were differentially expressed in the SAT of obesity patients, while seven genes (SOCS3, PRR5L, ABCG1, BRDT, B3GNT7, ZNF710, and RARRES1) were differentially expressed in the VAT of obesity patients." (PMID 30619480, 2018).
Achalasia (1 paper, 2024). A disorder of esophageal motility characterized by the inability of the lower esophageal sphincter to relax during swallowing and by inadequate or lacking peristalsis in the lower half of the body of the esophagus. "In this study, the mRNA expression levels of docking proteins 1 and 2 (DOK1 and DOK2) were analyzed and the underlying mechanisms that contribute to the onset of achalasia were investigated." (PMID 38792545, 2024). "The expression of DOK1 and DOK2 leads to the induction of IL-1β in the LES of achalasia patients, potentially leading to the esophageal motility disorder." (PMID 38792545, 2024). "DOK1 and DOK2 mRNA levels were significantly upregulated (p < 0.05) in the LES of patients with achalasia." (PMID 38792545, 2024). "The upregulation of DOK1 and DOK2 expression induces IL-1β expression in the LES of achalasia patients, which may contribute to the development of esophageal motility disorder." (PMID 38792545, 2024). "DOK1 and DOK2 mRNA levels were significantly increased in the LES of patients with achalasia." (PMID 38792545, 2024).
acute monocytic leukemia (1 paper, 2022). Acute monoblastic leukemia (AML-M5), is one of the most common subtypes of acute myeloid leukemia (AML) that is either comprised of more than 80% of monoblasts (AML-M5a) or 30-80% monoblasts with (pro)monocytic differentiation (AML-M5b). "Moreover, higher DOK2 expression levels were observed in M4 and M5 (acute monocytic leukemia) than in other FAB subtypes." (PMID 35321466, 2022).
adenoma (1 paper, 2013). A neoplasm arising from the epithelium. "Both Dok2 wild-type and KO C/KrasG12D mice developed typical grade II adenomas with uniform nuclei." (PMID 24255704, 2013).
colon cancer (1 paper, 2023). "DOK2 and MSRB3’s roles in the colon cancer immune microenvironment and the EMT process require further investigation, making them interesting subjects for future studies." (PMID 37884639, 2023).
Insulin resistance (1 paper, 2019). Increased resistance towards insulin, that is, diminished effectiveness of insulin in reducing blood glucose levels. "There is little information on the role of Dok2 in skeletal muscle or insulin resistance, however experiments in mice lacking Dok1 or Dok2 showed enhanced expression of Erk and Akt in myeloid cells." (PMID 31266232, 2019).
intestinal tumor (1 paper, 2022). "In particular, the number of relatively large (3.0 mm ≤ Φ), but not small (1.0 mm ≤ Φ < 3.0 mm), diameter tumors was significantly increased in Apc/Dok1/Dok2 mice compared with that in Apc mice, indicating that Dok-1/-2 deficiency enhances intestinal tumor growth." (PMID 36970719, 2022).
osteosarcoma (1 paper, 2025). A usually aggressive malignant bone-forming mesenchymal neoplasm, predominantly affecting adolescents and young adults. "The KM curve indicated that DOK2 acted as a protective factor, whereas NPW and RHBDL2 functioned as risk factors, all of which were associated with the survival rate of osteosarcoma patients." (PMID 40668798, 2025).
pancreatic cancer (1 paper, 2018). "Except for DOK2, this region contains the glial cell line-derived neurotrophic factor family receptor alpha 2, which could prompt pancreatic cancer cell growth and chemoresistance through downregulating tumour-suppressor gene PTEN via Mir-17-5p39." (PMID 30206226, 2018).
uterine carcinoma (1 paper, 2014). A carcinoma involving a uterus. "For uterine carcinoma, the somatic mutations on two genes were significantly enriched in protein pocket regions: DOK2 (P = 1.1 × 10-4) and NLRP7 (P = 3.2 × 10-4)." (PMID 25360158, 2014).